VIM (vimentin)
Diseases named in the same sentence as VIM in open-access papers (continued):
Sharing a sentence is not in itself a finding about the gene and the disease.
tumor (continued). "The tumor cells were strongly and diffusely positive for vimentin and CD68." (PMID 24959221, 2014). "As the cell lines differed significantly in expressing epithelial markers such as E-cadherin and Zona Occludens and mesenchymal markers like Vimentin, we hypothesized that these sublines might display tumor-cell heterogeneity occurring in vivo." (PMID 24959847, 2014). "Furthermore, within these cancers, vimentin expression correlates with accelerated tumor growth, increased metastatic potential, and poorer prognosis." (PMID 25162558, 2014). "The overexpression of annexin A10 protein, BCL-2-like protein, calgizzarin, HSP beta-6, RhoGAP-activating protein 7, transferrin, and vimentin among others referred to healthy samples may indicate the presence of tumor in bones." (PMID 24475253, 2014). "Vimentin was expressed in the cytoplasm of the tumour cells with weak to moderate intensity." (PMID 25047112, 2014). "In addition, VIM (vimentin) is characterized as an invasion/metastasis factor in tumor cells, which is transcriptionally regulated by HIF-1." (PMID 25151146, 2014). "As epithelial-mesenchymal transition (EMT) is one of the key events involved in invasion and metastasis of tumor cells, several epithelial markers (β-catenin and α1-catenin) and mesenchymal markers (Vimentin and Fibronectin) were tested by Western blot analysis." (PMID 25375090, 2014). "The efficacy mechanisms may involve in reinforcing immune responses, increasing expression of miR200c, E-cadherin and SMAD-7 and decreasing expression of TGF-β, ZEB1, Vimentin and N-cadherin in tumor tissues from the immunized mice." (PMID 24625224, 2014). "Furthermore, the tumor cells exhibited positive immunohistochemical staining for vimentin, CD21, CD35, D2-40 and leukocyte common antigen as well as negative staining for cytokeratin, CD20, CD30, CD117, epithelial membrane antigen and S-l00 (not shown)." (PMID 24708915, 2014). "Vimentin is known to positively influence tumor cell migration." (PMID 23785295, 2013). "The tumor cells expressed vimentin and some of them were also positive for S-100 protein." (PMID 23800162, 2013). "In this case, the tumor cells were positive for both CK and vimentin, and weakly positive for CD10." (PMID 23866935, 2013). "MET was confirmed at the molecular level by analyzing vimentin, snail and twist expression, which are established markers for mesenchymal tumor cells and are upregulated upon epithelial to mesenchymal transition as well as during the metastatic process of epithelial cancers." (PMID 23429996, 2013). "However, cells that would have migrated far from the tumor cannot be detected due limitations of the imaging field of view; additional analysis based on tissue sectioning and vimentin immunochemical tumor cell detection should further document this issue." (PMID 24069154, 2013). "Further, tumor cells did not induce synchronously expression of vimentin, which is often seen in EMT, to compensate for keratin loss." (PMID 23536778, 2013). "Immunohistochemical staining of the BIN-67-derived tumours revealed a diagnostic expression pattern that is similar to that reported in humans, notably intense expression of WT-1 and vimentin and lack of expression of inhibin." (PMID 23433318, 2013). "Additionally, ZEB2 upregulation of the EMT and tumor invasion-related genes, such as E-cadherin, vimentin, and metalloproteases, have been reported." (PMID 23658743, 2013). "In addition, we also found that in normal tumor-adjacent tissues both HNF4alpha and E cadherin was high expressed, while Snail, Slug, Fibronectin, N-cadherin and Vimentin were mostly low expressed." (PMID 24059685, 2013). "Furthermore, the expression of vimentin tended to be stronger and the expression of E-cadherin weaker at the invasive front, the interface between the tumor and stromal tissues, than in the center of the tumor proper." (PMID 23658677, 2013).
tumor (continued). "Moreover, we identified vimentin as an upstream modulator of EMT: forced expression of vimentin was sufficient to induce tumor cell transformation through the ILK/GSK-3β signaling axis." (PMID 23785295, 2013). "The tumor cells were strongly positive for Vimentin, Desmin and MyoD1." (PMID 23379991, 2013). "Silencing of vimentin or re-expression of E-cadherin in invasive cells also decreases their invasive phenotype; emphasizing that these genes play a major role in controlling the metastatic behavior of tumor cells." (PMID 23418515, 2013). "N-cadherin, E-cadherin and Vimentin expression in tumor tissues." (PMID 23520479, 2013). "Similarly, E-cadherin, β-catenin and vimentin levels were affected in MMTV-ErbB2/HdhQ111/Q111 tumours as compared to MMTV-ErbB2/HdhQ7/Q7 tumours." (PMID 23300147, 2013). "The acquired expression of vimentin in keratin-deficient tumor cells undergoing EMT may function as a compensatory mechanism to maintain cell integrity or may result from an activation of the vimentin promoter in the tumor setting." (PMID 23536778, 2013). "Also, the observations done on tumours with respect to the levels of ZO1, E-cadherin, β-catenin and vimentin were confirmed in an immunoblot analysis of extracts from PyVT/HdhQ7/Q7 and PyVT/HdhQ111/Q111 tumour cells." (PMID 23300147, 2013). "As expected, the human tumor cells in some of the PDX models stained weakly with vimentin." (PMID 23981300, 2013). "In the present case the tumor expressed cytokeratin, vimentin and keratin." (PMID 23758909, 2013). "The mesenchymal origin of the tumour was confirmed by high vimentin expression." (PMID 24289252, 2013). "Immunohistochemically, tumor cells expressed CK, VIM and P63 protein." (PMID 23236991, 2012). "Immunohistochemistry indicated that tumor cells were positive for Vimentin and CD99 (Mic-2)." (PMID 23329974, 2012). "Taken together, our studies suggest that HMGA1 promotes tumor progression through transcriptional networks that facilitate metastatic progression and a stem-like state, at least in part, by inducing the Twist1 and Vimentin, while repressing E-cadherin." (PMID 22276142, 2012). "In our study mesenchymal markers ZEB1 and vimentin were preferentially expressed in the tumor periphery, while the epithelial markers E-cadherin and β-catenin were reduced from cell junctions of some cells in the periphery, suggesting that these cells have undergone EMT." (PMID 23153292, 2012). "Also, ZEB2-mediated upregulation of EMT and tumor invasion related genes, such as E-cadherin, vimentin and metalloproteases, have been indicated." (PMID 22393452, 2012). "The tumour cells have an epithelial histology and express HCC-associated proteins such as Alpha-fetoprotein (AFP), Glypican 3, E-cadherin, CD10, CD326, HepPar1 and Vimentin." (PMID 22666492, 2012). "In addition, the up-regulation of several cytoskeletal network proteins, e.g., vimentin, beta-actin and keratin (type I cytoskeletal 15), also promotes tumour growth and metastasis." (PMID 23116199, 2012). "In agreement with this, nuclear β-catenin levels increased and a number of its target genes including cyclin D1, Zeb1 and vimentin, also known for their role in tumor proliferation and invasion, were induced upon exposure of naïve cells to CM from their senescent counterparts." (PMID 23272224, 2012). "We found that inactivation of miR-21 expression resulted in a significant decrease in the relative mRNA levels of EMT mesenchymal markers ZEB1 and Vimentin, and increased the relative mRNA level of epithelial marker E-cadherin in the tumor sphere cells under hypoxic conditions." (PMID 23272057, 2012).
tumor (continued). "Immunohistochemically, the tumour cells were positive for vimentin, actin, desmin, and myoglobin." (PMID 22792486, 2012). "Based upon these findings, it has been proposed that WFA might be useful as an anti-tumor agent since vimentin expression is frequently up-regulated as cancer cells undergo the epithelial to mesenchymal transition (EMT) associated with metastasis." (PMID 22720028, 2012). "Similarly, CDF decreased the mRNA levels of ZEB1, Vimentin, and Twist in the tumor sphere cells under hypoxic conditions." (PMID 23272057, 2012). "However, one focus of the primary tumor, as well as the area of invasion into the chest wall, displayed a more mesenchymal phenotype, staining strongly for vimentin and diffuse, cytoplasmic E-cadherin." (PMID 23049838, 2012). "The EGFR mutated SNAI1 reactivated tumor express TWIST1, VIM and CDH2 (sample 288) suggesting that TWIST1 and SNAI1 might interact to drive full mesenchymal phenotype." (PMID 22272264, 2012). "We confirmed the loss of E-cadherin and integrins and gain of vimentin in ACCS-M GFP, suggesting that the epithelial–mesenchymal transition (EMT) is a putative event in AdCC metastasis and induces tumor cell dissemination from the primary tumor site." (PMID 22931165, 2012). "Tumors in this study also showed very faint cytoplasmic vimentin staining in the bulk of the tumor." (PMID 23153292, 2012). "We focused on VIM and investigated whether VIM was regulated by tumor suppressive miR-138 and contributed to cancer cell migration and invasion in RCC cells." (PMID 22766839, 2012). "The tumor cells were positive for vimentin and smooth muscle actin strongly and uniformly." (PMID 22480303, 2012). "Notably, GB119 was able to recognize a vimentin-positive cell outside of the main tumor mass (arrowhead), i.e. infiltrating tumor cells." (PMID 22427947, 2012). "Immunohistochemically, the tumor cells are diffusely positive for vimentin and CD34." (PMID 22567356, 2011). "Transforming growth factor-β (TGF-β), fascin, nuclear factor-kappa B (NF-κB) p105, protein-kinase C-zeta (PKC-ζ), partioning-defective protein-6 (Par-6), E-cadherin and vimentin are tumor promoting molecules through mechanisms involved in cell dedifferentiation." (PMID 21390241, 2011). "The tumor cells were positive for vimentin, fascin and HLA-DR." (PMID 21961558, 2011). "CPMV nanoparticles were previously shown to bind surface vimentin on other human tumor cells." (PMID 24212937, 2011). "Immunohistochemically, tumor cells exhibit a positive reactivity for renin, vimentin and CD34." (PMID 21871063, 2011). "Vimentin is a antiangiogenesis target overexpressed on tumor endothelium in vivo." (PMID 22216242, 2011). "By multivariate survival analysis, tumour epithelial vimentin expression was significantly related to a shorter postsurgical survival, independently of the degree of histological differentiation, surgical margin status, tumour size (>30 mm) and lymph node metastases." (PMID 21448168, 2011). "The discrepancy between the mRNA level and protein level can be explained by the two following reasons: 1) although undifferentiated layers (basal and parabasal) have been reported to express EMT-related genes including VIM, their expression levels were much lower than tumor." (PMID 21533028, 2011). "Similarly, in the group of patients having cancers with high vimentin expression (>10% of cancer cells expressing), margin-positive surgical resection (P=0.04) and tumour size (P=0.04) were also predictors of a shorter postsurgical survival." (PMID 21448168, 2011).
tumor (continued). "However when CD133 populations were analyzed in CD44 by surface vimentin sorting, we found a subpopulation of cells for each tumor cell type that expressed all three surface markers." (PMID 24212937, 2011). "Several kinds of monoclonal antibody were used to evaluate tumor cells immunohistochemically and included anti-Vimentin, CD31, CD34, cytokeratin (CK AE1/AE3, 34 β-E 12, 5/6, and CAM 5.2), desmin, α-smooth muscle actin (α-SMA), myoglobin, myogenin, and Ki-67 (MIB-1) antibodies." (PMID 21329505, 2011). "In our material, all tumor cells were positive for vimentin, but at varying degrees." (PMID 21390241, 2011). "Immunofluorescence analyses of sections from xenografts harvested at week 10 after tumor cell transplantation or sections of patient biopsies showed that tumors in situ have clusters of E/M cells (EpCAM+/vimentin+) as well as clusters of epithelial cells (E-cadherin+/Vimentin−)." (PMID 21264259, 2011). "The neoplasia of the left testicle revealed a moderate vimentin expression." (PMID 21255434, 2011). "Tumour epithelial vimentin expression is a marker of mesenchymal differentiation and may be a useful marker of carcinomas with more aggressive behaviour." (PMID 21448168, 2011). "By immunohistochemical analysis, the membrane staining of the epithelial marker E-cadherin significantly increased in the pulmonary metastatic nodules compared to the primary SPC-A-1sci tumour, and otherwise the mesenchymal marker, vimentin, remarkably decreased in the pulmonary metastatic nodules." (PMID 20615257, 2010). "All tumour and normal stromal cells expressed the mesenchymal protein marker vimentin." (PMID 20407446, 2010). "Furthermore, Pea3 activates transcription of multiple neoplasia-associated genes, including MMP genes, COX-2, Twist, osteopontin, uPA, vimentin, MUC4, WT1, mammaglobin, cyclin D3 and HER2." (PMID 20107508, 2010). "Thus, understanding the correlation between overexpression of vimentin and tumor invasiveness still calls for additional studies." (PMID 20169076, 2010). "Tumor cells from a subset of cases were also associated with strong expression of vimentin (22/22, 100%) and an absence of CD117 expression (0%, 5/5)." (PMID 20979607, 2010). "Specifically, a group of 40 well-defined genes, classified according to their function, were able to distinguish between 2 different GBM signatures revealing the possible different proliferative potential in high grade GBM tumours (VIM, GLUL, PLK1, HUWE1, RPS4X...)." (PMID 20735813, 2010). "The ability of CPMV to efficiently visualize tumor neovasculature and differentiate arterial from venous tissues may now be attributed to upregulation of surface vimentin." (PMID 19412526, 2009). "Vimentin-positive tumours were significantly more often high grade tumours." (PMID 19695088, 2009). "A possible explanation for this unusual feature is that keratin expression may decrease, while vimentin expression may increase, as the tumour presents sarcomatoid dedifferentiation." (PMID 19830109, 2009). "Moreover, vimentin expressing tumours were usually positive for at least one of the basal type cytokeratins (CK5/6 or CK14 or CK17) (p < 0.001)." (PMID 19695088, 2009). "Stratifying the cases based on histology revealed that the significance of better survival for high tumour epithelial NF-κB p105 and vimentin expression was limited to ACs (P=0.03 and P=0.0004, respectively) and stromal NF-κB p105 and Par6 expression to SCCs (P=0.001 and P=0.0009, respectively)." (PMID 18854838, 2008). "IHC showed a diffuse strong positivity for CK and vimentin in the tumor cells." (PMID 17341294, 2007).
tumor (continued). "Vimentin expression in the tumour stroma may reflect a higher malignant potential of the tumour and may be a useful predictive marker for disease recurrence in CRC patients." (PMID 17325702, 2007). "Only very focal cytoplasmic staining was observed for vimentin, approximately 10% of the tumour cell nuclei were weakly immunopositive for oestrogen receptor, and there was strong cytoplasmic and nuclear labelling of both the squamous and glandular elements for p16." (PMID 17961245, 2007). "Moreover, similar antigenic expressions (for cytokeratins, vimentin, β-catenin, and E-cadherin) were identified between the lesions, suggesting common pathogenetic mechanisms in the histogenesis of these tumours." (PMID 18045453, 2007). "Vimentin expression was detected in the tumour stroma region." (PMID 17325702, 2007). "Vimentin and the "histiocytic" determinants (alpha-1-antitrypsin and alpha-1-antichymotrypsin) have been the only consistent immunohistochemical markers expressed by this tumor." (PMID 16504010, 2006). "In particular, we sought to determine the phenotype of N-cadherin+/E-cadherin−/vimentin+, as this has been implicated in epithelial–mesenchymal transition (EMT), a process important in the progression of neoplasia towards dedifferentiation and more ‘malignant’ states." (PMID 17031402, 2006). "The tumor may express receptors for progesterone while histological characteristics include positivity for vimentin and cytokeratin." (PMID 17090300, 2006). "tumor cells exhibited positivity for vimentin, EMA, NSE, chomogranin A, AE1/AE3 and WT1." (PMID 15777480, 2005). "tumor cells exhibited positivity for vimentin, NSE, AE1/AE3 and WT1." (PMID 15777480, 2005). "Genes such as COL1A2, VIM, and TGFB1/TGFB4, which are associated with tumor cell invasiveness and tissue remodeling, were not only expressed in infiltrative tumor cells but also broadly present in the surrounding peritumoral tissues influenced by the tumor milieu." (PMID 40725477, 2025). "Furthermore, APOL1, TNF, and VIM are co-expressed in myeloid cells, while APOL1 and TNF are also co-expressed in T cells and NK cells, indicating the association between APOL1 and the lactylation–PANoptosis axis in regulating tumor progression." (PMID 40649778, 2025). "The identification of a specific enrichment of EMT-associated proteins and immunomodulatory signals, such as PD-L1, within these EVs suggests that extracellular vimentin may be a key player in driving both cellular migration and immune evasion in the tumor microenvironment." (PMID 40618999, 2025). "Additionally, Vimentin-positive circulating tumor cells (Vim+ CTCs), Vascular Endothelial Growth Factor Receptor positive circulating tumor cells (VEGFR2+ CTCs), Programmed Death-Ligand 1 positive circulating tumor cells (PD-L1+ CTCs) were also associated with lung cancer diagnosis." (PMID 41211419, 2025). "Furthermore, PBX3 could affect the expression of genes associated with cytoskeletal remodeling and extracellular matrix degradation, such as MMPs and vimentin, thereby promoting tumor cells’ metastatic potential." (PMID 40508020, 2025). "TRIM67 overexpression, which may act like an oncogene, was reported to correlate with increased tumor growth, augmented tumor volume, elevated vimentin expression at tumor margins, and decreased overall survival in patient-derived oligodendroglioma-orthotopic implanted mice." (PMID 40426960, 2025). "To explore whether SpatialSNV is able to identify essential SNVs in tumorigenesis, we utilized transcriptomics data to divide the tumor section into the tumor (marked by EPCAM and other tumor-associated markers), tumor-adjacent margins (marked by VIM, COL1A2, PTPRC), and normal tissues." (PMID 40515555, 2025). "Although tumor cells may have vimentin expression, this marker lacks specificity for PHO." (PMID 41479782, 2025). "Notably, the primary tumor co-expressed vimentin while unexpectedly retaining E-cadherin." (PMID 40648806, 2025).